ERG (ETS transcription factor ERG)
Diseases named in the same sentence as ERG in open-access papers (continued):
Sharing a sentence is not in itself a finding about the gene and the disease.
lung fibrosis (2 papers, 2022 to 2024). "In fact, ERG function was found to be dysregulated in aging, and its loss both enhanced paracrine fibroblast activation in vitro and impaired lung fibrosis resolution in young mice in vivo." (PMID 37582200, 2024). "scRNA-seq of ERG deficient mouse lungs reveales transcriptional and fibrogenic abnormalities resembling those associated with aging and human lung fibrosis, including reduced number of general capillary (gCap) ECs." (PMID 35879310, 2022). "Loss of endothelial ERG enhances paracrine fibroblast activation in vitro, and impairs lung fibrosis resolution in young mice in vivo." (PMID 35879310, 2022). "To assess whether ERG-deficient mice developed lung fibrosis, we measured hydroxyproline content followed by Masson’s trichrome staining on WT and EGR CKO lungs at 45 days following the last dose of tamoxifen." (PMID 35879310, 2022). "To evaluate the function of ERG on pulmonary vascular repair and lung fibrosis, we used bleomycin to induce lung fibrosis in both WT and ERG CKO mice." (PMID 35879310, 2022). "We also found that in WT but not in ERG CKO mouse lungs, areas of active remodeling exhibited abundant deposition of Collagen IV and Laminin IV, suggesting that ERG-mediated basement membrane protein secretion plays an active role during lung fibrosis resolution." (PMID 35879310, 2022). "Given that ERG CKO mice, as well as aged mice, exhibited capillary abnormalities and impaired lung fibrosis resolution post-injury, we postulated that dysregulation of ERG in ECs may underpin IPF." (PMID 35879310, 2022). "Here, we demonstrated that ECs lacking ERG enhanced fibrogenic responses in lung fibroblasts in vitro and perpetuated lung fibrosis in vivo." (PMID 35879310, 2022).
lymph node metastasis (2 papers, 2020 to 2024). "We have revealed that SCD is notably overexpressed in Caucasian patients, as well as in patients with Gleason score 8, stage N1 lymph node metastasis, or ERG fusion." (PMID 39351232, 2024). "Nuclear protein expression was linked to advanced tumor stage, high Gleason score, presence of lymph node metastasis, early biochemical recurrence, and ERG-positive cancers (p < 0.0001 each)." (PMID 33339518, 2020).
malignant rhabdoid tumors (2 papers, 2016 to 2019). "Almost all cases of ES are negative for ERG gene rearrangement and according to detection by IHC or fluorescence in situ hybridization (FISH), 90% of malignant rhabdoid tumors show nuclear deficiency of INI1, with the inactivation of SMARCB1." (PMID 31615564, 2019). "All of their patients with malignant rhabdoid tumors had negative test results for ERG, suggesting that ERG may be a useful marker to distinguish ES from malignant rhabdoid tumors with loss of INI1." (PMID 27776545, 2016).
myeloid sarcoma (2 papers, 2021 to 2024). A tumor mass composed of myeloblasts or immature myeloid cells. "ERG was expressed in a majority of myeloid sarcoma and was not expressed in any patients with BPDCN." (PMID 38933637, 2024).
myeloproliferative disorder (2 papers, 2017 to 2024). A clonal hematopoietic stem cell disorder, characterized by proliferation in the bone marrow of one or more of the myeloid (i.e., granulocytic, erythroid, megakaryocytic, and mast cell) lineages. "Furthermore, dysregulation of XIST, RUNX1, SON, ERG and STAT1 was observed, contributing to myeloproliferative disorders." (PMID 38474215, 2024).
neuroendocrine tumor (2 papers, 2013 to 2017). "The tumors in TRAMP mutants had a distinct stromal character to that in PB-MYC and ERG/PTEN mice, even when the neuroendocrine tumors were not included in the analysis." (PMID 27935821, 2017).
psoriasis (2 papers, 2021 to 2023). An autoimmune condition characterized by red, well-delineated plaques with silvery scales that are usually on the extensor surfaces and scalp. "ERG is a key transcription regulator of cluster 4 fibroblasts, which have been identified as comprising a cluster of fibroblasts involved in vascular function in psoriasis." (PMID 37816883, 2023). "Depending on the role of the particular ERG in the pathogenesis of psoriasis, its differential expression may either promote or limit the growth of psoriatic plaques in a disease-affected area." (PMID 34575702, 2021).
Stroke (2 papers, 2020 to 2022). Sudden impairment of blood flow to a part of the brain due to occlusion or rupture of an artery to the brain. "At 56 d post stroke, numerous ERG+ cells were observed in the peri-ischemic areas after 90-min t-MCAO and p-MCAO." (PMID 32492968, 2020). "Further, early reperfusion increased the number of ERG+ endothelial cells during acute (1 and 7 d post stroke) and chronic periods (56 d post stroke)." (PMID 32492968, 2020). "Similarly, immunohistochemistry 1 d post stroke showed ERG+ endothelial cells within the ischemic areas after 90-min t-MCAO (I’) and p-MCAO (J’)." (PMID 32492968, 2020). "Thus, we next investigated PDGFRβ+ and ERG+ cell expression patterns 7 d post stroke." (PMID 32492968, 2020). "At day 1 post-stroke, co-localizations of Ascl1 and the endothelial marker CD31 and the endothelial transcription factor ERG appeared within the ischemic boundaries." (PMID 36535938, 2022).
Thrombocytopenia (2 papers, 2023 to 2024). A reduction in the number of circulating thrombocytes. "The characterization of a (mouse) germline ERG variant (p.S305P) residing in BMF (thrombocytopenia) also alludes to the possibility of ERG as a low penetrant leukemic predisposition gene." (PMID 37377909, 2023).
viral infection (2 papers, 2022 to 2024). "Nine TFs such as DUX, SPI1, and ERG targeted the total eight genes, and may collaboratively regulate the downstream pathways of metabolic and virus infection, which are the pivotal paths in the SGA." (PMID 39687015, 2024).
acute myelomonocytic leukemia (1 paper, 2025). "Patient ALMA_4_PB (0–5 years, female; coverage 2.12x), presenting acute myelomonocytic leukemia (FAB M4), was inaccurately classified as MPAL T-Lymphoblastic/Myeloid subtype, with nanopore genomics showing FUS::ERG fusion presence." (PMID 40730747, 2025).
adenoma (1 paper, 2017). A neoplasm arising from the epithelium. "In addition, interductal fibroblast-like cells expand in PB-MYC and ERG/PTEN tumors, whereas in TRAMP PCa they expand little and stromal cells invade into intraductal adenomas." (PMID 27935821, 2017).
adenosquamous carcinoma (1 paper, 2017). A carcinoma composed of malignant glandular cells and malignant squamous cells. "Cells transformed by both AR/AKT/ERG and c‐MYC/sgPTEN generated heterogeneous tumors including adenocarcinoma and adenosquamous carcinoma, consistent with a recent report." (PMID 28297567, 2017).
androgen insensitivity syndrome (1 paper, 2022). Androgen insensitivity syndrome (AIS) is a disorder of sex development (DSD) characterized by the presence of female external genitalia, ambiguous genitalia or variable defects in virilization in a 46,XY individual with absent or partial responsiveness to age-appropriate levels of androgens. "We identify novel allosteric surfaces which are compromised in androgen insensitivity syndrome, and reinforced by AR’s oncoprotein cofactor, ERG, and by DNA binding motifs." (PMID 35447082, 2022).
arterial disease (1 paper, 2025). "Our report discusses the possibility that loss-of-function variants in ERG may act as a risk factor for arterial disease." (PMID 40630904, 2025).
asthma (1 paper, 2017).
autoimmune disease (1 paper, 2025). A disorder resulting from loss of function or tissue destruction of an organ or multiple organs, arising from humoral or cellular immune responses of the individual to their own tissue constituents. "Furthermore, across all groups, motifs found in less accessible regions upon stimulation were associated primarily with TFs in the ELF family, PU.1, and ERG which are known to be involved in autoimmune disease." (PMID 40103826, 2025).
bone marrow failure (1 paper, 2026). "The patient had suspected hemophagocytic lymphohistiocytosis, and recent reports link ERG variants to a bone marrow failure phenotype, possibly explaining the presentation better than the available OMIM entry." (PMID 41116046, 2026).
coagulopathy (1 paper, 2019). "Deletion of ERG disrupts regulation of coagulation, leading to a coagulopathy associated with thrombosis and/or bleeding in liver and lung." (PMID 31676784, 2019). "Interestingly, acute treatment with a red blood cells-targeted TM was able to restore the levels of TAT, an early biomarker of coagulopathy and thrombosis, showing that loss of TM expression is in part responsible for the prothrombotic phenotype observed in ERG-deficient mice." (PMID 31676784, 2019).
dermatomycosis (1 paper, 2021). Superficial infections of the skin or its appendages by any of various fungi. "The results suggests that it is necessary to inhibit the expression of ERG, CYP, and EF3 related genes as well as fat metabolism in order to effectively deal with dermatomycosis caused by TM." (PMID 33827426, 2021).
End Stage Liver Disease (1 paper, 2017). Final stage of a liver disease when the liver failure is irreversible and LIVER TRANSPLANTATION is needed. "Co-IP revealed that ERG interacts with SMAD3 in HUVEC and in Hepatic Sinusoidal Endothelial Cells (HSEC) isolated from transplant patients with end-stage liver disease." (PMID 29026072, 2017).
endothelial dysfunction (1 paper, 2023). In vascular diseases, endothelial dysfunction is a systemic pathological state of the endothelium (the inner lining of blood vessels) and can be broadly defined as an imbalance between vasodilating and vasoconstricting substances produced by (or acting on) the endothelium. "Linking these findings to the present study, it could be speculated that under basal conditions, LINC00607 guides BRG1 to ERG target genes and during endothelial dysfunction to pro-angiogenic genes to maintain an open and accessible chromatin state for ERG." (PMID 36700983, 2023).
Granuloma (1 paper, 2025). A compact, organized collection of mature mononuclear phagocytes, which may be but is not necessarily accompanied by accessory features such as necrosis. "Histopathology was critical: biopsies demonstrated exuberant granulation tissue with ERG-positive capillaries and a dense CD38-positive plasma cell infiltrate without granulomas." (PMID 40700331, 2025).
heart failure (1 paper, 2019). Inability of the heart to pump blood at an adequate rate to meet tissue metabolic requirements. "Data on ERG expression in failing hearts has been inconsistent, few studies report a reduction of ERG expression in heart failure." (PMID 30841920, 2019).
hepatic angiosarcoma (1 paper, 2026). "Ultrasound-guided liver biopsy confirmed high-grade hepatic angiosarcoma, with tumor cells showing ERG positivity and weak CD31 expression, and lacking hepatocellular or epithelial markers." (PMID 42028496, 2026).
Hypercalcemia (1 paper, 2017). An abnormally increased calcium concentration in the blood. "VDRM2 significantly reduces TMPRSS2:ERG positive VCaP xenograft tumor growth without causing hypercalcemia or significant weight loss in mice and VDRM2 is stable in cells that overexpress CYP24A1." (PMID 28591703, 2017). "Two challenges that limit VDR agonist use clinically are hypercalcemia and the cooperation of VDR with ERG to hyper-induce the 1α,25-dihydroxyvitamin D3 metabolizing enzyme, CYP24A1, thus reducing VDR activity." (PMID 28591703, 2017). "Using the VCaP TMPRSS2:ERG positive cell line as a model, we found that a nonsecosteroidal CYP24A1 resistant VDR agonist, VDRM2, substantially reduces growth of xenograft tumors without inducing hypercalcemia." (PMID 28591703, 2017).
influenza (1 paper, 2023). An acute viral infection of the respiratory tract, occurring in isolated cases, in epidemics, or in pandemics; it is caused by serologically different strains of viruses (influenzaviruses) designated A, B, and C, has a 3-day incubation period, and usually lasts for 3 to 10 days. "(G) IF for tdTomato, ERG, and Endomucin-1 in H1N1-infected Atf3-tdTm mice at 22 dpi demonstrates an increase in Atf3-positive ECs in the alveolar space after influenza (inset marked by white box)." (PMID 37233732, 2023).
injury (1 paper, 2017). Damage inflicted on the body as the direct or indirect result of an external force, with or without disruption of structural continuity. "As elevated inflammatory cytokines are associated with fibrogenesis, we assessed the impact of TNF-α inhibition on ERG expression and SMAD3 activity by co-administration of the TNF-α antagonist etanercept in an acute CCL4-induced liver injury." (PMID 29026072, 2017).
insulinoma (1 paper, 2022). "In this paper we also performed experiments with an insulinoma cell line, and we showed that ERG K+ channels are expressed in this model and that the treatment with a specific inhibitor (E4031) caused a sharp reduction in cell viability." (PMID 36142530, 2022).
intraductal carcinoma (1 paper, 2023). "This pooled analysis verified that PTEN loss (p = 0.012), ERG positivity (p = 0.022), and intraductal carcinoma (IDC) (p = 0.001) were associated with a decreased likelihood of pathologic response." (PMID 37109028, 2023). "PTEN loss, ERG positive, or intraductal carcinoma seem to be associated with worse pathologic response." (PMID 37109028, 2023).
invasive breast carcinoma (1 paper, 2014). A carcinoma that infiltrates the breast parenchyma. "The ERG-induced mesenchymal-like signature positively correlated with TMPRSS2-ERG prostate tissues and invasive breast cancer mRNA expression datasets reflecting a general ERG-driven pattern of malignancy." (PMID 24504051, 2014).
liver disease (1 paper, 2017). "Moreover, ERG represents a promising candidate biomarker for assessing EndMT in liver disease." (PMID 29026072, 2017).
lymphatic malformation 14 (1 paper, 2026). "In contrast, due to poor genotype–phenotype matching of the gene description in OMIM, standard analysis software missed a VUS in ERG (Lymphatic Malformation 14, MIM #620602) in case 25, which was detected by LR-GS." (PMID 41116046, 2026).
lymphoid leukemia (1 paper, 2023). A malignant lymphocytic neoplasm of B-cell or T-cell lineage involving primarily the bone marrow and the peripheral blood. "As such, the mechanism proposed here identifies HDAC3 inhibition as a potential therapeutic route for the treatment of ERG-driven and ERG-dependent myeloid and lymphoid leukemias." (PMID 37735473, 2023).
lymphoid neoplasm (1 paper, 2024). A neoplasm composed of a lymphocytic cell population which is usually malignant (clonal) by molecular genetic and/or immunophenotypic analysis. "Previous studies have demonstrated that aberrant modulation of EBF1, ETS1, ERG, and RUNX transcription factors has significant effects on lymphoid neoplasms derived from B cell progenitors." (PMID 38926853, 2024).
malignant glioma (1 paper, 2019). A grade III or grade IV glioma arising from the central nervous system. "Since ERG expression like cFos and EGR1 has been reported to correlate with radioresistance and poor prognosis in malignant glioma, we wondered if NMDAR signaling was also capable of regulating Top2β-dependent cFos expression in GBM cells." (PMID 30841565, 2019).
mastocytosis (1 paper, 2023). A clonal myeloproliferative neoplasm characterized by the proliferation and accumulation of neoplastic mast cells in one or multiple organs or organ systems. "Further studies on the relevance of oncogenes FOXQ1, TWIST1, and ERG as second-hit mutations in mastocytosis and novel therapeutic targets are needed." (PMID 37762215, 2023). "Importantly, three oncogenes—FOXQ1, TWIST1, and ERG—were identified as differentially methylated in mastocytosis patients, for the first time." (PMID 37762215, 2023). "The identification of three oncogenes differentially methylated in mastocytosis patients, i.e., FOXQ1, pro, and ERG, was an interesting finding." (PMID 37762215, 2023).
neuroendocrine carcinoma (1 paper, 2023). A malignant neuroendocrine neoplasm composed of cells containing secretory granules that stain positive for NSE and chromogranin. "Of note, ERG was not expressed in the C1022 human tumor and PDX neuroendocrine carcinoma, however a strong expression of synaptophysin and chromogranin was measured confirming the NE phenotype." (PMID 37305585, 2023).
osteoarthritis (1 paper, 2022). A noninflammatory degenerative joint disease occurring chiefly in older persons, characterized by degeneration of the articular cartilage, hypertrophy of bone at the margins and changes in the synovial membrane. "In osteoarthritis, circserPine2 may provide a potentially effective treatment strategy for osteoarthritis by reducing chondrocyte apoptosis and promoting extracellular matrix anabolism through the miR-1271/ERG pathway." (PMID 35154330, 2022).
papillary renal cell carcinoma (1 paper, 2019). A rare subtype of renal cell carcinoma, arising from the renal tubular epithelium and showing a papillary growth pattern, which typically manifests with hematuria, flank pain, palpable abdominal mass or nonspecific symptoms, such as fatigue, weight loss or fever. "A 3-mRNA signature consisting of ERG, RRM2, and EGF was constructed to predict survival in papillary renal cell cancer with satisfactory accuracy." (PMID 31886185, 2019).
Pca (1 paper, 2022). "Our study showed high expression levels of these genes in ERG fusion-positive PCa patients and their associated survival risk." (PMID 35508713, 2022). "Given the recurrence of ERG fusion in ~50% of patients, these newly found antioxidant functions might provide a therapeutic target for ERG positive Pca patients." (PMID 35508713, 2022). "In this context, metabolic profiling of ERG fusion-positive PCa patients exhibits altered metabolism of glucose, citrate, and fatty acid associated with high Gleason score." (PMID 35508713, 2022). "Here we report a function of ERG under metabolic stress which warrants further studies as a therapeutic target for ERG fusion positive PCa." (PMID 35508713, 2022). "Opposingly, ERRα is reported to form a reciprocal regulatory loop with ERG fusion which can steer PCa progression." (PMID 35508713, 2022). "Our study on metabolic stress and ERG fusion-driven antioxidant functions is supportive of PCa metabolic program." (PMID 35508713, 2022). "Recent studies of androgen receptor (AR) independent PCa with altered transcriptional circuits strengthen the possibility of ERG fusion-driven programs." (PMID 35508713, 2022). "Inhibition of PGC1α-ERG axis driven transcriptional program results in apoptosis and reduction in PCa xenografts." (PMID 35508713, 2022). "The role of ERG in regulating ROS is not well understood during PCa development." (PMID 35508713, 2022). "Together our study identifies ERG- PGC1α axis during metabolic stress which might be crucial for PCa progression." (PMID 35508713, 2022). "Although antioxidant genes like SOD3, TXN, and SOD1 has been associated with PCa aggressiveness and metastasis, none have shown a direct relationship with ERG fusion." (PMID 35508713, 2022). "We reveal that ERG drives the expression of antioxidant genes; SOD1 and TXN, benefitting PCa growth." (PMID 35508713, 2022).